ZIC5 (Zic family zinc finger 5)
Description:
Essential for neural crest development, converting cells from an epidermal fate to a neural crest cell fate. Binds to DNA (By similarity).
Tractability: No criterion of Open Targets' tractability assessment is met for any kind of drug.
Gene: Protein-coding gene on chromosome 13 (99,962,964 to 99,971,767, reverse strand). Ensembl gene ENSG00000139800.
Subcellular location: Nucleus
Subcellular location (Human Protein Atlas): Nucleoplasm; Vesicles
Gene Ontology:
Molecular function: sequence-specific double-stranded DNA binding; DNA-binding transcription factor activity, RNA polymerase II-specific; RNA polymerase II cis-regulatory region sequence-specific DNA binding; RNA polymerase II transcription regulatory region sequence-specific DNA binding
Biological process: central nervous system development; regulation of transcription by RNA polymerase II
Cellular component: nucleus
Genetic constraint (gnomAD): Loss-of-function variants: 20 observed, 21.55 expected, observed/expected ratio (o/e) 0.93, 90% interval 0.65 to 1.35. The synonymous counts are far from expectation, so gnomAD's model fits this gene poorly and the ratio says little. Missense variants: 938 observed, 693.2 expected, observed/expected ratio (o/e) 1.35, 90% interval 1.28 to 1.43. Synonymous variants: 476 observed, 324.91 expected, observed/expected ratio (o/e) 1.47, 90% interval 1.36 to 1.58.
Homologues: Orthologues: chimpanzee ZIC5 (99% identical), macaque ZIC5 (97% identical), dog ZIC5 (94% identical), pig ZIC5 (93% identical), rat Zic5 (87% identical), mouse Zic5 (87% identical), tropical clawed frog zic5 (57% identical), zebrafish zic5 (53% identical). Paralogues in human: ZIC2 (37% identical), ZIC1 (37% identical), ZIC3 (34% identical), ZIC4 (32% identical), GLI3 (25% identical), GLI2 (24% identical), GLIS3 (21% identical), GLI1 (19% identical), GLIS1 (19% identical), GLIS2 (18% identical), ZXDC (16% identical), ZXDA (16% identical), and 2 more.
Diseases named in the same sentence as ZIC5 in open-access papers:
ZIC5 is named in the same sentence as 25 diseases in open-access papers, as found by Europe PMC text mining. Sharing a sentence is not in itself a finding about the gene and the disease. The quoted sentences say what the papers report.
glioma (8 papers, 2019 to 2023). A benign or malignant brain and spinal cord tumor that arises from glial cells (astrocytes, oligodendrocytes, ependymal cells). "In conclusion, circ_0007534 acts as a glioma regulator by inhibiting miR-761 and promoting ZIC5 protein expression." (PMID 36505874, 2022). "An elevation of ZIC5 was frequently observed in a series of cancer types including glioma, hepatoma, non-small-cell lung cancer, and prostate cancer." (PMID 35571493, 2022). "RT-qPCR and western blot analyses showed that overexpression of miR-761 significantly inhibited the expression of ZIC5 protein in glioma cells." (PMID 36505874, 2022). "Significant upregulation of ZIC1/3/4 was found in brain low-grade glioma patients, while ZIC5 was downregulated." (PMID 34475426, 2021). "In KEGG analysis, Neuroactive ligand-receptor interaction (hsa04080) was related to the functions of ZIC5 alternations in glioma." (PMID 34475426, 2021). "Li GF and colleagues suggested that the circ-DDX42/miR-761/ZIC5 axis is likely to act as a glioma treatment target." (PMID 33392180, 2020). "For instance, hsa_circ_0007534 promoted the progression of glioma through the miR-761/ZIC5 regulatory loop." (PMID 31179240, 2019). "Additionally, exosomal circ-HIPK3 from TMZ-resistant glioma cells regulates glioma via the miR-421/ZIC5 axis, thereby enhancing its drug resistance." (PMID 37779868, 2023). "Exosome-mediated circ-HIPK3 enhances TMZ resistance via modulating the miR-421/ZIC5 axis and promotes tumorigenesis in vitro and in vivo; its expression in serum exosomes can be used as a biomarker for diagnosis of TMZ-resistant glioma." (PMID 35382838, 2022).
prostate carcinoma (7 papers, 2016 to 2025). A carcinoma that arises from epithelial cells of the prostate gland. "Regarding transcription factor-driven and signaling pathway activation, SNHG4 is overexpressed under the regulation of SP1, promoting prostate cancer cell proliferation, migration, and invasion by sponging miR-377 to upregulate the oncogene ZIC5." (PMID 41301542, 2025). "In the previous studies, SNHG4, as a miR-377 sponge, was demonstrated to elevate the expression of ZIC5 in prostate carcinoma." (PMID 33088220, 2020). "Of these three genes, HELLS and ZIC5 protein expression was strongly associated with GS ≥ 7 prostate cancer, while we were not able to confirm this relation on protein level for ZIC2." (PMID 27191985, 2016). "Interestingly, we found that ZIC1, ZIC2, ZIC4 and ZIC5 were all up-regulated in Gleason grade 3 embedded in GS 4 + 3 = 7 prostate cancer on RNA level." (PMID 27191985, 2016). "In prostate cancer, SNHG4 relieved the miR-377-induced suppression of ZIC5 by acting as a ceRNA, therefore promoting ZIC5-mediated growth and metastasis." (PMID 33744866, 2021). "In prostate cancer, SNHG6 modulates cancer cell sensitivity to paclitaxel by sponging miR-186, SNHG12 influences tumorigenesis through targeting miR-133b, and SNHG4 enhances ZIC5-mediated tumor growth and metastasis via the regulation of miR-377." (PMID 41301542, 2025). "ZIC5 mRNA was up-regulated 17 fold (p = 8.4E–07), ZIC2 8 fold (p = 1.3E–05) and HELLS 2 fold (p = 0.006) in Gleason grade 3 tumor glands derived from GS 4 + 3 = 7 as compared to GS 3 + 3 = 6 prostate cancer." (PMID 27191985, 2016).
hepatocellular carcinoma (4 papers, 2022 to 2025). A malignant tumor that arises from hepatocytes. "High expression levels of certain ZIC genes are associated with poor prognosis and more aggressive cancer phenotypes, as observed with ZIC2 in clear cell renal cell carcinoma and ZIC5 in hepatocellular carcinoma." (PMID 40952541, 2025). "Recent studies showed that ZIC5 modulates Wnt/β-catenin signaling to influence the growth and metastasis of hepatocellular carcinoma cells and glucose metabolism in colorectal cancer." (PMID 36127329, 2022). "Similarly, ZIC5 increased the expression of β-catenin and Cyclin D1 in the Wnt/β-catenin pathway, leading to enhanced invasion and metastasis of hepatocellular carcinoma." (PMID 40952541, 2025). "For example, it was found that characteristic high ZIC5 expression promotes progression and metastasis of lung and hepatocellular carcinoma through mechanisms involving, respectively, enhanced CCNB1/CDK1 complex expression and Wnt/β-catenin signaling stimulation." (PMID 36127329, 2022). "ZIC5 promotes the malignant phenotype of hepatocellular carcinoma (HCC) by promoting β‐catenin signaling and COL1A1 expression." (PMID 40318167, 2025).
melanoma (4 papers, 2019 to 2025). A malignant, usually aggressive tumor composed of atypical, neoplastic melanocytes. "Reiko's findings suggest that the overexpression of ZIC5 can enhance the invasiveness of melanoma primarily by activating the FAK and STAT3 signalling pathways." (PMID 40344305, 2025). "Previously, we had identified Zic family member 5 (ZIC5) as a critical survival transcription factor in melanoma, colorectal cancer, prostate cancer, cholangiocarcinoma, and PDAC cells." (PMID 40318167, 2025). "A previous study reported that ZIC5 overexpression promotes melanoma aggressiveness and metastatic spread." (PMID 36127329, 2022). "Moreover, ZIC5 was reported to drive melanoma EMT progression and metastasis through transcriptional downregulation of E-cadherin expression." (PMID 36127329, 2022). "In turn, ZIC5 inhibition enhanced transcriptional elongation of CDH1 (E-cadherin), whereas ZIC5 overexpression triggered PDGFD-mediated activation of FAK and STAT3 signaling, thereby promoting melanoma aggressiveness." (PMID 36127329, 2022).
colon cancer (3 papers, 2021 to 2022). "GSE127960 includes the gene expression profiling of the human colon cancer cell lines HCT116 with ZIC5 wild-type (ZIC5 WT) and ZIC5 knockout (ZIC5 KO) replicates." (PMID 35996085, 2022). "Supporting this evidence, a previous study showed that ZIC5 interacts with the β-catenin/TCF4 complex to repress GLUT1 expression and regulate glucose metabolism in HCT 116 colon cancer cells." (PMID 36127329, 2022).
colorectal cancer (3 papers, 2022 to 2025). A primary or metastatic malignant neoplasm that affects the colon or rectum. "ZIC5 expression is also enhanced in colorectal cancer and is associated with the tumour pathological stage." (PMID 36282887, 2022). "Further, in colorectal cancer cells, it is shown that ZIC5 forms a complex with TCF7L2 and β‐catenin to act as a transcriptional repressor of SLC2A1." (PMID 40318167, 2025). "ZIC5 knockdown induces apoptosis in colorectal cancer, pancreatic cancer and cholangiocarcinoma cells and additively or synergistically induces apoptosis with anti‐cancer agents such as oxaliplatin and gemcitabine." (PMID 36282887, 2022). "Because ZIC5 knockdown induces apoptosis in pancreatic cancer, cholangiocarcinoma and colorectal cancer cells, we assessed the effect of patulin and LL‐Z1640‐2 on these cell lines." (PMID 36282887, 2022). "Another study revealed that ZIC5 stimulated colorectal cancer cell proliferation via the CDK1/CDC25c pathway, and depletion of ZIC5 exerted antineoplastic effects." (PMID 36127329, 2022).
meningioma (3 papers, 2010 to 2023). A generally slow growing tumor attached to the dura mater. "We examined the mRNA and protein expression of human ZIC1, ZIC2, ZIC3, ZIC4 and ZIC5 genes in meningiomas in comparison to other brain tumors, using RT-PCR, analysis of published microarray data, and immunostaining." (PMID 20199689, 2010). "ZIC1, ZIC2, and ZIC5 are novel molecular markers for meningiomas whereas ZIC4 expression is highly selective for medulloblastomas." (PMID 20199689, 2010). "RT-PCR analysis revealed that ZIC4 expression is highly enhanced in medulloblastoma, in a sharp contrast to the expression levels in whole brain, while ZIC1, ZIC2 and ZIC5 are expressed both in the meningioma and medulloblastoma." (PMID 20199689, 2010). "Our results indicate that the expression of ZIC1, ZIC2 and ZIC5 is a conserved feature of meningioma." (PMID 20199689, 2010). "ZIC1, ZIC2 and ZIC5 transcript levels in meningiomas were higher than those in whole brain or normal dura mater, whereas all five ZIC genes were abundantly expressed in medulloblastomas." (PMID 20199689, 2010). "This is consistent with our observation that ZIC1, ZIC2 and ZIC5 mRNA levels are higher in meningiomas than in normal brain tissues." (PMID 20199689, 2010). "The transcriptional levels of ZIC1, ZIC2, and ZIC5 in meningiomas were found to be significantly higher than those in normal dura mater and could serve as new molecular markers for meningiomas." (PMID 37479694, 2023). "The mRNA levels of ZIC1, ZIC2 and ZIC5 were higher in meningioma than in dura mater." (PMID 20199689, 2010).
lung carcinoma (2 papers, 2025). "It specifically targets and reduces ZIC5 level, an important transcription factor in lung cancer progression." (PMID 40344305, 2025). "Immunohistochemical analysis has validated that the level of ZIC5 expression is notably elevated in lung cancer tissues when contrasted with normal tissues." (PMID 40344305, 2025).
brain tumors (1 paper, 2010). "However, the expression of the other ZIC genes (ZIC2, ZIC3, ZIC4, and ZIC5) has not been investigated in medulloblastoma or other brain tumors." (PMID 20199689, 2010).
breast carcinoma (1 paper, 2022). "Among these six genes, five were hypermethylated (GABRA5, ZIC5, GRAMD4, RSPH3, and VCAN), and one was hypomethylated (CSMD1) in breast cancer samples of cases compared to controls." (PMID 36627894, 2022).
cholangiocarcinoma (1 paper, 2022). A carcinoma that arises from the intrahepatic biliary tree (intrahepatic cholangiocarcinoma) or from the junction, or adjacent to the junction, of the right and left hepatic ducts (hilar cholangiocarcinoma). "Our results showed that LL‐Z1640‐2 and patulin are promising compounds that decrease ZIC5 expression levels and induce apoptosis in various cancer cells, including melanoma, BRAF‐inhibitor resistant melanoma, pancreatic cancer and cholangiocarcinoma cells." (PMID 36282887, 2022).
colorectal tumor (1 paper, 2021). "Developmental transcription factors like these are often found to be ectopically re-expressed in specific tumor cells, and this is the case for ZIC5 and FOXD1 in serrated colorectal tumor cells." (PMID 33423702, 2021).
COVID-19 (1 paper, 2022). A disease caused by infection with severe acute respiratory syndrome coronavirus 2. "We identified 230 LUAD/COVID-19 DEGs and constructed a risk score containing 7 genes (BTK, CCL20, FURIN, LDHA, TRPA1, ZIC5, and SDK1) that could classify LUAD patients into two risk groups." (PMID 35733175, 2022). "The analyses of these 7 gene expression levels between different clinical features suggested that BTK, SDK1, CCL20, LDHA, and ZIC5 may serve as effective biomarkers for screening and characterizing patients with LUAD/COVID-19 at different stages." (PMID 35733175, 2022).
holoprosencephaly (1 paper, 2021). Holoprosencephaly (HPE) is a complex brain malformation resulting from incomplete cleavage of the prosencephalon, occurring between the 18th and 28th day of gestation, and affecting both the forebrain and face, which results in neurological manifestations and facial anomalies of variable severity. "Although CMA was performed on all simplex cases (n = 141), a causal variant was identified in the form of chromosomal deletion in only three cases (14DG1134, 16DG1465, and 15DG0267); the latter is a case of holoprosencephaly linked to a large homozygous deletion that encompasses ZIC2 and ZIC5." (PMID 34645488, 2021).
laryngeal squamous cell carcinoma (1 paper, 2022). A squamous cell carcinoma that arises from the larynx. "CAPRIN1 promoted laryngeal squamous cell carcinoma glycolysis and chemoresistance by the regulation of ZIC5." (PMID 35571493, 2022).
lung adenocarcinoma (1 paper, 2025). A carcinoma that arises from the lung and is characterized by the presence of malignant glandular epithelial cells. "This study aims to explore the effects of silencing Zic family member 5 (ZIC5) on glucose metabolism and disulfidptosis in lung adenocarcinoma (LUAD) cells." (PMID 40366858, 2025).
pancreatic cancer (1 paper, 2022). "Recently, we disclosed that the overall survival of patients with ZIC5‐expressing pancreatic cancer was significantly lower than that of patients without ZIC5 expression." (PMID 36282887, 2022).
tumor (13 papers, 2015 to 2025). "ZIC5 was proposed to support cancer cell growth, invasion, and migration, and its expression was associated with drug resistance and tumor metastasis." (PMID 36127329, 2022). "We also conducted qRT‐PCR analyses to measure the abundance of hsa‐miR‐29b‐3p and ZIC5 transcripts in the xenograft tumours." (PMID 40344305, 2025). "The analysis revealed that ZIC5 was significantly overexpressed in both the LUAD cohort (tumour = 515 cases, normal = 59 cases, p < 0.001) and the LUSC cohort (tumour = 503 cases, normal = 52 cases, p < 0.001)." (PMID 40344305, 2025). "When tumor‐bearing mice were injected intravenously with ZIC5‐targeting small interfering RNA, tumor volume was significantly reduced by gemcitabine treatment." (PMID 40318167, 2025). "Mechanistically, OIP5‐AS1 contributes to tumorigenesis via its modulation of the hsa‐miR‐29b‐3p/ZIC5 axis, revealing a sophisticated regulatory circuitry that governs critical aspects of tumour biology." (PMID 40344305, 2025). "After the tumor volume was engrafted to approximately 100 mm3, atelocollagen with chemically modified siRNA against ZIC5 (stZIC5), randomized control siRNA (stNeg), or atelocollagen alone (Control) was intravenously injected." (PMID 40318167, 2025). "ZIC5 promotes tumor progression through metabolic pathways, possibly inhibiting EPAS1 activity or competing for the regulation of glycolytic genes." (PMID 40366858, 2025). "We found that patulin and LL‐Z1640‐2 reduced ZIC5 protein levels and induced apoptosis in many tumour cell lines, including BRAF inhibitor‐resistant melanoma cells, but not in NHMs." (PMID 36282887, 2022). "Our results provide new insights into the effects of patulin and suggest that patulin is a promising anti‐cancer reagent for many types of tumour cells that express ZIC5." (PMID 36282887, 2022). "Our results provide new insights into the effects of LL‐Z1640‐2 and suggest that this compound is a promising anti‐cancer reagent for many types of tumour cells that express ZIC5." (PMID 36282887, 2022). "ZIC5 knockdown also inhibits proliferation and tumour growth in non‐small cell lung cancer and hepatocellular carcinoma." (PMID 36282887, 2022). "One-hundred patients (24%) showed nuclear ZIC5 staining in < 1% of the tumor cells, 32 patients (8%) expressed ZIC5 in 1–5% of the tumor cells and 15 patients (4%) expressed ZIC5 in > 5% of the tumor cells." (PMID 27191985, 2016). "ZIC2, ZIC5, and C2 overlap in the age-dependent tumor-normal difference and age-related tumor-tumor comparisons." (PMID 28027300, 2016). "ZIC5 was expressed in > 1% of tumor cells in 15/29 (52%) of evaluable GS 4 + 3 = 7 patients and 55/135 (41%) of GS 3 + 4 = 7 patients (p = 0.28)." (PMID 27191985, 2016). "In this analysis, we identified subtype‐specific events for Epi‐LumB tumors involving either DNA copy number loss or CpG promoter methylation over DZIP1, TNFSF11, ZIC5, COL4A2, COL4A1 and PCDH8 indicating candidate tumor suppressor genes." (PMID 25468711, 2015). "who could show that ZIC5 is highly upregulated in NSCLC tumor tissues, and they suggested that ZIC5 may act as an oncogene by influencing CCNB1 and CDK1 complex expression." (PMID 37228492, 2023). "In particular, the most intense ZIC5 staining was found in metastatic tumor tissues." (PMID 36127329, 2022). "However, ZIC5 depletion led to a reduction in tumor growth, and this effect was enhanced by the combination of Enz treatment and ZIC5 knockdown." (PMID 36127329, 2022). "Despite mounting evidence of the pervasive influence of ZIC5 in multiple cancer types, the association between ZIC5 and AR signaling or with PCa tumor aggressiveness has not been fully defined." (PMID 36127329, 2022). "Therefore, we uncovered a novel positive feed-forward loop linking AR and ZIC5 in PCa tumor malignant progression." (PMID 36127329, 2022).